CD4 (CD4 molecule)
Diseases named in the same sentence as CD4 in open-access papers (continued):
Sharing a sentence is not in itself a finding about the gene and the disease.
tumor (continued). "In contrast, a previous report showed that CD4 + T lymphocytes in a Th2-type tumor microenvironment can promote metastasis by regulating the pro-tumor properties of tumor-associated macrophages (TAMs), as opposed to limiting or eradicating malignant cells by engaging cytotoxic mechanisms." (PMID 36759775, 2023). "We discovered that the high-risk patients had an immunosuppressive phenotype, which is only accompanied by a multitude of M0 macrophage infiltration; conversely, the low-risk subgroup was named active anti-tumor immune with many antitumor immune cells (e.g. CD4+ T cells, CD8+T cells, B cells)." (PMID 37223030, 2023). "However, similar to the EBNA3C-deficient tumours, the ENBA3A knockout tumours grow more slowly and with an increased infiltration of CD4+ and CD8+ T-cells." (PMID 36836878, 2023). "Collectively, these results show a significantly higher infiltration with CD8 + TILs in BAP1- or PTEN-mutated ccRCCs both at the invasive margin and in the tumor periphery, while counts for CD4 + or FOXP3 + cells were found to depend more on the histological subtype than the mutational status." (PMID 36562826, 2023). "Notably, tumor regression also associated with a significantly increased CD4 subset expressing Granzyme K (FC3-GZMK)." (PMID 37185301, 2023). "In addition, Caprin-1 recruits CD4+T cells and tumor associated macrophages (TAMs) infiltration in TME, indicating Caprin-1High cancer cells are likely to escape from immune surveillance and fail to respond to immunotherapy." (PMID 38082307, 2023). "Additionally, the infiltrated CD4+T cells and tumor associated macrophages (TAMs) were increased in Caprin-1High tissues." (PMID 38082307, 2023). "Furthermore, they underline the importance of cDC1 and CD4+ T-cell help for effective CTL-based anti-tumor immunity." (PMID 36639382, 2023). "Higher levels of circulating CD4+ T lymphocytes were linked to smaller tumor sizes in GC patients." (PMID 36776289, 2023). "To explore the immune response that is associated with CT26 tumor rejection, we combined prophylactic pCT26-5 DNA vaccination with anti-(α)CD4 or αCD8 T-cell depleting antibodies, to delineate the extent to which the observed tumor control is reliant on either T-cell subset." (PMID 37244905, 2023). "High levels of infiltration of CD8 + T cells, CD4 + T cells, neutrophils, B cells, M1-polarized macrophages and dendritic cells determine the pre-existing anti-tumor immune activity of patients and are associated with better prognosis and longer survival in patients receiving immunotherapy." (PMID 37752452, 2023). "Upon tumor progression, the patients were re‐transferred with >95% pure mutation‐specific Th1 cells, which effectively suppressed the tumor volume, indicating that CD4+ T cells can also be harnessed for ACT treatment." (PMID 37829505, 2023). "Many CD8 + and CD4 + T cells in the tumor are associated with poor prognosis." (PMID 37542141, 2023). "Indeed, there is increasing interest in targeting MHC class II-restricted antigens in immunotherapies and mutated neoantigens that stimulate anti-tumour CD4+ T cell responses have recently been identified in other syngeneic tumour models." (PMID 37153625, 2023). "The results displayed that the risk score was negatively correlated with immune infiltration score (Stromal score, Immune score and ESTIMATE score); furthermore, the risk score was negatively correlated with tumor-infiltration lymphocytes (TILs) (such as CD4 + T cells, NK, and CD8 + T cells)." (PMID 37596527, 2023). "Tregs expression was significantly increased in the tumor groups of all grades compared to the normal endometrial group.The upregulation of CD4 expression in T cells in the ITME was positively associated with high cancer grade, cancer stage, and myometrium invasion." (PMID 37927462, 2023).
tumor (continued). "At tumor site, significant increases in neutrophils, monocytes and macrophages (p<0.05) were observed in the Lipo LPS-exposed group compared to controls, associated with a significant decrease in B cells as well as CD4+ and CD8+ T cells (p<0.05)." (PMID 37223101, 2023). "Furthermore, the reduction in tumor growth was associated with an increased accumulation of CD4+ and CD8+ T cells within the solid tumors." (PMID 36839766, 2023). "Besides, one phase II clinical trial reported that a CCA patient who participated in the adoptive cell therapy experiment and transfused mutation-specific CD4+ T cells after chemotherapy failure, and the tumor achieved partial remission 7 months later." (PMID 37064120, 2023). "Interestingly, this group of cells appeared to be spatially located close to HRS tumor cells with loss of MHC-II that can escape from the anti-tumor function of CD4+ T cells." (PMID 36959853, 2023). "It has been demonstrated that A2AR is broadly expressed on several immune cells, including tumor-associated macrophages (TAMs), CD4+ regulatory T cells (Tregs), effector CD4+ T cells, and cytotoxic T lymphocytes at distant levels, in the TME of major solid cancers." (PMID 37834375, 2023). "Through cytokine secretion, the CD8+ and CD4+ Th1 T cells are the primary effector cells associated with a good prognosis, while other CD4+ T cell subsets (Th2, Th17), myeloid suppressor cells, M2 macrophages, and Treg cells cause tumour promotion." (PMID 37295047, 2023). "Similar to CD8+ T cells subpopulation, the treatment with nanoconjugate and DC/shIL-10R/TAg caused a significantly increased influx of CD4+ T cells into tumor tissue, not only in comparison to MTX + DC/shIL-10R/TAg group, but also in relation to other HES-MTX-treated groups of mice." (PMID 37033926, 2023). "In addition, GSDME expression is associated with the proliferation and function of tumor-associated CD4+ T cells, CD8+ T cells, TAMs, NK cells, etc50." (PMID 37705746, 2023). "In addition, the expression of NSUN2 was found to be associated with the infiltration of multiple types of tumor cells, including memory B cells, resting memory CD4+ T cells, activating memory CD4+ T cells, and resting NK cells." (PMID 37217462, 2023). "However, in contrast to many other solid tumor types, infiltration of CD8+ and CD4+ T cells in ccRCC tumors is often linked to a poor prognosis and advanced tumor grade, highlighting T cell dysfunction during the progression of RCC." (PMID 37190141, 2023). "In this analysis, prognostic Risk Scores were also positively correlated with CD4+ T cells and myeloid dendritic cell infiltration, suggesting that these prognostic risks are may related to tumor immune regulation." (PMID 37064114, 2023). "We also found Tregs, and CD4 memory resting T cells infiltrated more in patients with high‐risk, Tregs are well‐known immunosuppressive cells, which could reduce the anti‐tumor function of other immune cells by promoting immune escape in the TIME." (PMID 36056909, 2023). "In contrast, the increase in HDAC2 and B2M mutants in CRC appeared to be associated with a differentiated CD4+ Th2 subpopulation, which could affect tumor promotion." (PMID 37046620, 2023). "We speculate that enhanced MHC-II expression on B7-H3-deficient tumor cells together with professional antigen-presentation cells leads to a greater antigen presentation to cytolytic CD4+ T lymphocytes." (PMID 36869048, 2023). "The high-risk subgroup had a higher proportion of anti-inflammatory macrophage M2 cells, while the low-risk subgroup had an increased proportion of resting memory CD4 T cells, activated dendritic cells and mast cells, indicating the potential anti-tumor effects of the low-risk subgroup." (PMID 37880674, 2023). "A patient with metastatic cholangiocarcinoma has a CD4+ T-cell epitope ERBB2IP-E805G; CD4+Th1 cells targeting mutated antigens could mediate tumor regression." (PMID 37965271, 2023).
tumor (continued). "We noted that a large proportion of genes specifically enriched within tumor-associated Treg cells compared with CD4+ Tconv cells (|FC| > 4, q < 0.05) under steady-state conditions were induced at high levels within CD4+ or CD8+ Tconv cells upon Treg cell ablation." (PMID 38100544, 2023). "The major immunosuppressive cells in the TME of TNBC include myeloid-derived suppressor cells (MDSCs), tumor-associated macrophages (TAMs) with an M2 phenotype, tumor-associated neutrophils (TANs) with an N2 phenotype, regulatory T (Treg) cells, and CD4+ helper T (Th) cells." (PMID 37570775, 2023). "Pre-clinical studies have indicated that vaccines against the mutated protein may elicit an anti-tumor response from CD4+ and CD8+ T cells; clinical trials are ongoing." (PMID 37046685, 2023). "In the case of CRC, intratumoral infiltration by CD8+ and CD4+ T cells is concerned with a favourable prognostic factor increasing patients’ overall survival rate, whereas M2 tumour-associated macrophages (M2-TAMs) infiltration promotes cancer cell proliferation and increases metastatic potential." (PMID 38067326, 2023). "More importantly, PD1+CD4+ T cells were found to be associated with more numbers in tumour tissues than paratumour tissues, and the top 20 markers of these cells in tumour tissues (logfc > 0.95, p < .001) were associated with a lower probability of overall survival in ESCC." (PMID 36855810, 2023). "However, in the later phase, tumors can evade the immune defenses and progress by creating an immunosuppressive TME containing M2 tumor-associated macrophages (TAMs), CD4+ Th2 cells, and, especially, regulatory T cells (Tregs)." (PMID 38140230, 2023). "Here, we provided a direct evidence that dysregulation of various types of immune cell between tumor and non‐tumor was associated with EC patients, including down‐regulated immune activation cells (CD4+/CD8+ T_cells and DCs) and upregulated immunosuppression cells (macrophages, MDSCs and Tregs)." (PMID 36226375, 2023). "Notably, tumor resection caused significant changes in the proportion and absolute number of CD4+CD57+T and CD4+PD-1+T, both of which showed a significant decrease." (PMID 36925914, 2023). "T cell infiltration to the tumor bed was modulated by filaggrin mutational state, since patients with wild-type filaggrin showed significant down-regulation of CD4+ naïve T cells, central memory T cells, and natural killer T cells, while Th1 cells were significantly upregulated." (PMID 37284199, 2023). "Furthermore, we observed that activated CD4 memory T cells, M0 macrophages, and tumor-associated macrophages were the most prevalent immune stromal cells in the tumor microenvironment." (PMID 37665670, 2023). "Additionally, low amounts of tumor-stromal collagen were also linked to low levels of CD4+ TILs (P = 0.046), CD8+ TILs (P = 0.09), and tertiary lymphoid structures (P = 0.001)." (PMID 37477731, 2023). "Moreover, we demonstrated overexpression of IGSF6 was associated with a high density of CD8+ T cell and CD4+ T cell tumor-infiltrating lymphocytes." (PMID 37989761, 2023). "Notably, CD4+ T cell presence in the tumor microenvironment is one of the key mechanisms that underly the observed effects of IRX4647-treatment on immune response and on anti-neoplastic effects." (PMID 37689790, 2023). "It remains to be determined whether auto-antibody responses against neo-antigens are widespread in HGSC or other cancers and if this is due to creation of new CD4+ T cell epitopes by tumor mutations." (PMID 36943460, 2023). "Each extra unit of CD4+ concentration in the residual tumor reduces the risk of death by 35.8%." (PMID 36765559, 2023).
tumor (continued). "Similarly, in a mouse model of cervical carcinoma expressing hLF, impaired tumor growth was associated with an increase in CD4+ and CD8+ T lymphocytes in peripheral blood." (PMID 37111542, 2023). "However, the mechanisms of CD4+ T cell driven anti-tumor immunity in response to ICB in MHC-I-deficient MMRd cancers remain to be fully investigated." (PMID 37492581, 2023). "PAR2 knockout mice exhibited robust enhancement of immunosuppressive cells, including myeloid-derived suppressor cells and tumor-associated macrophage and largely alleviated antitumor CD4+ T cell functions in tumor microenvironment, leading to promotion of tumor progression." (PMID 38159863, 2023). "Finally, a study of 23 patients receiving TARE for metastatic breast cancer showed that increased frequency of baseline PD-1 expression by CD4+ TILs in the tumor microenvironment was associated with clinical response." (PMID 37511193, 2023). "On the one hand, the response can promote tumor dissemination and metastasis through the action of CD4+ Th2 effector cells, which regulate the pro-tumor properties of tumor-associated macrophages via IL-4 expression, and IL-4 is upregulated in many mouse and human tumors." (PMID 37429945, 2023). "Furthermore, low-risk patients possessed a higher fraction of some tumor-suppressor TILs (such as NK cells activated, Macrophages M1, and T cells CD4 memory activated), associated with improved RFS." (PMID 37498396, 2023). "Tregs, which are usually known for maintaining immune homeostasis by suppressing the immune system’s self-reactive immune responses, are the main tumor-promoting CD4+ helper T-cell subpopulation, and are associated with poor clinical prognosis in patients with NSCLC." (PMID 38136314, 2023). "While Akt activity has been implicated in the control of alternative splicing in tumor cells, recent studies are emerging that indicate that similar functions may exist in CD4 T cells." (PMID 36710922, 2023). "Since MHC-mediated activation of CD4+ T cells is vital for tumor immunity, the loss of such MHC II expression in premalignant ISCs may enhance tumor initiation and contribute to the acceleration of tumor progression by HFD." (PMID 36817228, 2023). "In addition, tumor-derived adenosine also recruits CD4+ Treg cells to the TME, causing an immunosuppressive microenvironment." (PMID 37834375, 2023). "In addition, CLDN18 was significantly associated with markers of activated CD8 + T cells and CD4 + T cells after adjusting for tumor purity." (PMID 37438735, 2023). "Interestingly, we identified a HLA-DRhigh CD206+ macrophage subgroup that was significantly associated with the tumor-infiltrating CD4+ T lymphocytes and showed different surface costimulatory molecule expression than that of the HLA-DRlow/-CD206+ subgroup." (PMID 36864443, 2023). "Similarly, a high density of CD4+ T cells in the tumor margin was independently associated with favourable OS or DFS." (PMID 35392957, 2022). "HNSCC tumors had an abundance of tumor-associated macrophages (36.8 ± 11.9%), neutrophils (22.8 ± 9.78%) and CD4+ T cells (10.5 ± 8.04%), Tregs (7.50 ± 7.15%) and CD8+ T cells (6.84 ± 9.18%) whereas B cells (4.46 ± 6.88%), NK cells (3.76 ± 2.30%) and DCs (2.98 ± 4.04%) were less present." (PMID 36268020, 2022). "Our data showed that low-risk populations were accompanied by a multitude of anti-tumor immune cell infiltration (e.g. CD4+ T cells, B cells, CD8+ T cells, and NK cells), whereas high-risk populations were accompanied by a multitude of M0 macrophage infiltration." (PMID 36311789, 2022). "Moreover, CD8+IL-4+ and CD4+IL-4+ T cells had positive associations with tumor size and stage of the disease." (PMID 36376825, 2022). "Immune surveillance was considered as the vital part of anti-tumor immunity, however, tumor cells might escape the surveillance by reducing CD4+ and CD8+ lymphocytes causing lymphocytopenia." (PMID 36157419, 2022).
tumor (continued). "The CD4+ T cells are associated with the enhanced tumor immune response." (PMID 34894177, 2022). "Correspondingly, deficiencies in the number or functionality of immune cells in TME, such as CD8+ cytotoxic T cells, CD4+ helper cells, natural killer cells or B cells lead to increased susceptibility to carcinogen-induced tumors and spontaneous tumor development." (PMID 36323670, 2022). "Classically, the CD4 Th1 subtype is associated to anti-tumor immunity." (PMID 36362027, 2022). "These mRNA vaccines efficiently delivered TAA-encoding mRNA to DCs and subsequently activated antitumor CD8+ and CD4+ T-cell immune responses, reduced tumor-associated immunosuppression, and finally significantly decreased tumor growth and metastasis in different murine tumor models." (PMID 36432733, 2022). "However, systemic TSLP induction from the skin causes an effective CD4+ T cell-mediated anti-tumor immune response at the site of developing cancer in the breast." (PMID 35432341, 2022). "Finally, PD-1+ICOS+CD4+ Th TILs were demonstrated to recognize both tumor-associated antigens and tumor-specific neoantigens." (PMID 36451828, 2022). "In this study, WGCNA was performed using DLBCL gene expression data to search for gene modules highly associated with activated memory CD4+ T cells infiltration in order to explore the impact of the tumor microenvironment and identify potential biomarkers of DLBCL." (PMID 35711924, 2022). "Furthermore, immune responses of CD4+ T cells against tumor-associated antigens were observed following oxaliplatin treatment in chemotherapy-naïve patients with mCRC (colorectal cancer)." (PMID 36304169, 2022). "Breakage of CD4+ T cell tolerance to tumor-associated antigens (TAAs)." (PMID 35327364, 2022). "The differential analysis revealed markedly increased infiltration of cancer-associated fibroblasts, endothelial cells, macrophages, particularly M2 macrophages, and monocytes in high-risk patients, and high CD4+ Th1 cell infiltration, for anti-tumor immune response, in low-risk patients." (PMID 35382776, 2022). "Indeed, as with CD8+ T cells, CD4+ T cells were critical for the anti-tumor effect mediated by CaMKK2 deficiency." (PMID 36309495, 2022). "Additionally, the ablation of the microbiome caused an enhanced expression of PD1 on tumor-infiltrating CD4+ and CD8+ T cells, thus, enhancing the immunotherapeutic efficacy of anti-PD1 monoclonal antibodies (mAbs)." (PMID 35741028, 2022). "In the univariate analysis, the factors of age, smear and culture findings, site of TB, comorbidity with tumor, white blood cell count, neutrophil count, and CD4/CD8 ratios were substantially linked to true-positive (also known as sensitivity) and false-negative QFT-GIT outcomes." (PMID 36288019, 2022). "Notably, CRIM1 expression was positively linked to the level of infiltration by CD8+ T-cells, endothelial cells, and neutrophils, and negatively linked to NK, B-cells, CD4+ T-cells, tumor purity, macrophage M1, and Tregs." (PMID 35600360, 2022). "Th17 cells are a newly discovered CD4+T cell subgroup associated with anti-tumor activities." (PMID 35222443, 2022). "In addition, the gene expression profile of cytotoxic CD4+ T cells in tumor tissues is associated with the clinical response of metastatic bladder cancer patients treated with anti- programmed death-ligand 1 therapy." (PMID 36059506, 2022). "In this study, we observed that the gene signature was closely associated with infiltrating immune cells in the tumor microenvironment as memory B cells, activated memory CD4 + T cells, follicular helper T cells, and M0 macrophages were abundant in patients with high risk scores." (PMID 36133439, 2022). "We additionally found that activation of CD4 + T cells and M1 macrophages can promote anti-tumor immunity and have low infiltration in EGFR mutated NSCLC, which could limit the killing efficiency of CD8 + T cells." (PMID 35992815, 2022).